IL17A (interleukin 17A)
Diseases named in the same sentence as IL17A in open-access papers (continued):
Sharing a sentence is not in itself a finding about the gene and the disease.
pertussis (67 papers, 2009 to 2025). A contagious bacterial respiratory infection caused by Bordetella pertussis. "Through the research on the live aP vaccine BPZE1 and the outer-membrane vesicle pertussis vaccine, secretory IgA (SIgA) and IL-17a, which induce eradication of mucosal aP bacteria, are triggered only through nasal administration." (PMID 38276680, 2024). "LASSO modeling also revealed positive association between pertussis IgG levels with CB concentrations of T-cell-derived cytokines IL-2, IL-17A, and IL-31, but in contrast to tetanus, APRIL was negatively associated with pertussis, as was IL-33." (PMID 37251388, 2023). "A linear mixed-effects model for the repeated measures revealed significant correlations between APRIL and IFN-γ with 12-month tetanus IgG levels and APRIL, BAFF, IL-21, IL-17A, and sCD14 with 12-month pertussis IgG levels." (PMID 37251388, 2023). "Single-nucleotide polymorphisms (SNPs) in candidate genes, MBL2, IL17A, TNFα, VDR, and IL10 were genotyped in a unique Dutch cohort of symptomatic clinically confirmed (ex-)pertussis patients and in a Dutch population cohort." (PMID 26894582, 2016). "In CB samples, plasma IL-2, IL-17A, IL-31, sCD14, and switched memory B cells were positively associated, whereas APRIL, IL-33, non-switched memory B cells, and plasmablasts were negatively associated with 12-month pertussis IgG levels." (PMID 37251388, 2023). "Using a least absolute shrinkage and selection operator (lasso) regression model, cord blood (CB) plasma IL-2, IL-17A, IL-31, and soluble CD14 (sCD14) were positively associated with pertussis IgG levels at 12 months, while CB plasma concentrations of APRIL and IL-33 were negatively associated." (PMID 37251388, 2023).
Cognitive impairment (66 papers, 2015 to 2026). Abnormal cognition is characterized by deficits in thinking, reasoning, or remembering. "Recent studies have reported that IL-17A was involved in the early pathological process of AD, causing cognitive impairments and synaptic dysfunction Neutralization of IL-17A restored the function of Aβ-induced neuroinflammation and memory impairment." (PMID 35392087, 2022). "To ascertain the mechanisms by which IL-17A deletion ameliorates cognitive impairment caused by repeat sevoflurane exposure in neonatal mice, we used western blot analysis to examine the changes in the protein levels of IL-17A, NF-κB p65, COX-2 and iNOS." (PMID 35758051, 2022). "Furthermore, the mice on a high-salt diet developed cognitive impairment due to cerebral endothelial dysfunction, which was associated with an increase in Th17 polarization and IL-17A plasma level in the small intestine." (PMID 35935951, 2022). "Likewise, IL17A may cause cellular damage and associated cognitive impairment, as seen in our present study, by promoting Aβ1–42 accumulation." (PMID 26509545, 2015). "Prior animal models have supported the role of IL‐17A in AD pathogenesis, including neuroinflammation, neurodegeneration, and progressive cognitive deficits." (PMID 40781580, 2025). "In one study, neonatal mice exposed to sevoflurane showed increased IL-17A expression in the hippocampus; deletion or inhibition of IL-17A attenuated sevoflurane-induced cognitive impairment by reducing hippocampal neuroinflammation." (PMID 40948499, 2025). "The administration of an IL-17A neutralizing antibody in an Aβ-injection mediated AD mouse model ameliorates cognitive impairment and neuroinflammation, underscoring the functional significance of IL-17A in AD pathogenesis." (PMID 40469524, 2025). "A positive correlation was found between cognitive impairment and IL-17A at baseline (P=0.029) and D1 (P=0.003), D3 (P=0.013), and D7 (P=0.001)." (PMID 37878890, 2023). "IL-17A deletion protects against long-term cognitive impairment induced by repeated sevoflurane exposure in neonatal mice." (PMID 35758051, 2022). "Recent studies show that NF-κB is a downstream effector of IL-17A, which plays a role in postoperative cognitive impairment after surgical anesthesia by activating the NF-κB signaling pathway of aged rats." (PMID 35758051, 2022). "Regarding cognitive impairment, a study claims that increases in Th17 and interleukin (IL)-17A reduces nitric oxide production, thereby facilitating cognitive dysfunction in mice fed with excess dietary salt." (PMID 36386524, 2022). "IL-17A deletion ameliorated long-term cognitive impairment induced by multiple sevoflurane exposure in neonatal mice, inhibited the activation of the NF-κB signaling pathway, and led to alleviated neuroinflammation." (PMID 35758051, 2022). "Our findings reveal that repeated sevoflurane exposure induces significant long-term cognitive impairment, and that IL-17A deletion can prevent these deficits in neonatal mice." (PMID 35758051, 2022). "As for IL-17, it has been shown that exposure of microglia to IL-17A results in activation and increased production of proinflammatory cytokines, and IL-17A-neutralizing antibodies prevented neuroinflammation and cognitive impairment in rodents." (PMID 30733703, 2019). "Our previous data indicated that IL-17A was involved in LPS-induced cognitive impairment in aged rats." (PMID 30501622, 2018). "Taken together, our results suggest that IL-17A was involved in LPS-induced neuroinflammation and cognitive impairment in aged rats via microglial activation." (PMID 26373740, 2015). "In conclusion, our results suggest that IL-17A is involved in LPS-induced neuroinflammation and cognitive impairment in aged rats via microglial activation." (PMID 26373740, 2015). "This study aims to explore the role of IL-17A in LPS-induced neuroinflammation and cognitive impairment." (PMID 26373740, 2015).
Cognitive impairment (continued). "The present study aims to explore the role of IL-17A in LPS-induced neuroinflammation and cognitive impairment." (PMID 26373740, 2015). "Our results showed that the freezing behavior of animals treated with LPS was decreased, whereas pretreatment with IL-17A Abs was able to partially reverse the cognitive deficits seen following LPS treatment." (PMID 26373740, 2015). "In an attempt to ameliorate this LPS-induced cognitive impairment, we injected IL-17A Abs 30 min before LPS injection." (PMID 26373740, 2015). "Additionally, γδ T cells producing IL-17A have been reported to contribute to cognitive impairments and synaptic deficits in the triple-transgenic (3xTg) AD mouse model." (PMID 40469524, 2025). "Recently, a study has reported that the administration of blocking anti-IL-17A antibodies could rescue Aβ-induced cognitive impairment and neuroinflammation." (PMID 35935951, 2022). "The cognitive impairment was comparatively less severe in IL-17A KO mice." (PMID 35758051, 2022). "For example, elevated frequencies of IL-17-producing CD3+ CD8− cells have been demonstrated in Parkinson’s disease, and a polymorphism in the IL-17A gene was shown to increase the risk of cognitive impairment in PD." (PMID 34360808, 2021). "In sum, we come to a conclusion that anti-IL-17A treatment may improve neuroinflammation and oxidative stress by inactivation of NF-κB pathway, eventually alleviating cognitive impairment of aged rats with sevoflurane anesthesia." (PMID 30342469, 2018). "These in vivo experiments indicate that IL-17A may be involved in LPS-induced cognitive impairment and may play a detrimental role in it." (PMID 26373740, 2015). "In an AD mouse model, administration of anti-IL-17A antibody to block IL-17A generation could decrease the neuroinflammation induced by Aβ-42 injection, reduced neuronal neurodegeneration, and improve the cognitive impairment of the mice." (PMID 35459141, 2022). "The role of IL-17A in neurodegenerative diseases such as MS has been widely confirmed; however, little is known about whether IL-17A is involved in LPS-induced neuroinflammation and cognitive impairment." (PMID 26373740, 2015). "Therefore, the data presented here show that IL-17A Abs administration could prevent the cognitive deficits seen in LPS-treated animals." (PMID 26373740, 2015). "By establishing an animal model of IL-17A overexpression, we discovered that IL-17A increases the level of TNF-α in the brain through the TLR4/NF-κB signalling pathway, aggravates neuroinflammation, and thus exacerbates cognitive impairment." (PMID 38098004, 2023). "Another study showed a dose-dependent effect of IL-17 on hippocampal long-term potentiation through the activation of IL-17A receptor and p38MAPK in mice with EAE, while the lack of IL-17A ameliorates EAE-related cognitive deficits." (PMID 36189272, 2022). "Hence, we infer that the increased levels of IL-17A in brain regions related to social cognition of the HTX-gestated offspring may further contribute to the cognitive impairments evidenced by the performance of these offspring in the marble burying test." (PMID 38752179, 2024). "Although similar mechanisms are involved in senile postoperative cognitive impairment as well as sevoflurane neurotoxicity to the developing brain, there has been no study on the role of IL-17A in long-term cognitive impairment induced by repeated sevoflurane exposure." (PMID 35758051, 2022). "Moreover, IFN-γ (P = 0.335) and IL-4 (P = 0.410) levels were similar between patients with and without cognitive impairment, but IL-17A was enhanced in patients with cognitive impairment compared to those without cognitive impairment (P < 0.001)." (PMID 36386524, 2022).
Cognitive impairment (continued). "Moreover, Th1 (P = 0.003), Th17 (P < 0.001), IFN-γ (P = 0.014), and IL-17A (P < 0.001) were inversely related to MMSE scores, but only Th17 (P < 0.001) and IL-17A (P < 0.001) were increased in patients with cognitive impairment compared with those without cognitive impairment." (PMID 36386524, 2022).
inflammatory skin disease (66 papers, 2012 to 2026). Inflammatory skin disorders covers a broad category that includes many conditions ranging in severity, from mild itching to grave medical health complications These disorders are common in people of all ages and races. "IL-17A has been clearly linked to the pathogenesis of inflammatory skin disease; thus, to further detect IL-17A–producing cells in leprosy skin lesion, single-cell suspensions were prepared from dermis." (PMID 36389696, 2022). "Other genes, such as IL-21R, GSDMC, CCR7, TLR9, HAS1/3, IL-17A, IL-22, and CXCL10, have been previously identified as genes associated with various inflammatory skin disorders." (PMID 38612783, 2024). "In etiologic studies of acne and inflammatory skin disease, interleukin-17A (IL-17A) is found to play a driving role." (PMID 38205472, 2023). "The increase in asymmetric SC self‐renewal divisions in this hyperproliferative inflammatory skin disease was found to be IL17A‐dependent." (PMID 33524216, 2021). "Thus, evidencing the importance of the IL-17A/IL-17AR axis in inflammatory skin diseases such as AD." (PMID 30650525, 2019). "In addition, we successfully reproduced a psoriatic epidermal phenotype using IL-17A, suggesting the potential usage of a self-assembled RSE in modeling and investigating the pathogenesis of inflammatory skin diseases or in drug testing for these diseases." (PMID 35745784, 2022). "Various reports suggest that IL-22, as opposed to IL-17A, contributes more to the development of chronic lesions and excess type 2 deviations in inflammatory skin diseases derived from SA." (PMID 36076953, 2022).
myocardial infarction (65 papers, 2012 to 2026). Gross necrosis of the myocardium, as a result of interruption of the blood supply to the area, as in coronary thrombosis. "A study of 981 patients with myocardial infarction found that high serum levels of IL-17(commonly refers to as IL-17A) were associated with a lower risk of death and recurrent myocardial infarction." (PMID 39502194, 2024). "For instance, low serum IL-17A has been associated with recurrent major cardiovascular events and increased mortality in patients with acute myocardial infarction, suggesting a protective role of IL-17A." (PMID 36830855, 2023). "For example, in patients with acute myocardial infarction low serum IL-17A levels have been linked with mortality and recurrent major cardiovascular events, suggesting a protective role for IL-17A." (PMID 35008981, 2022). "Deficiency of IL-17A or γδ-T cells (main producers of IL-17 in the heart) alleviated left ventricular dysfunction after myocardial infarction." (PMID 33868315, 2021). "Focusing on IL-17A, high levels of bioactive IL-17A were associated with destruction in RA but also during myocardial infarction." (PMID 32983142, 2020). "Recently, it was shown that interleukin-17A (IL-17A) is involved in the pathophysiology of reperfusion injury and associated with infarct size (IS) in experimental models of myocardial infarction." (PMID 29166391, 2017). "Il-17a was increased in Tdag8-deficient mice in a model of myocardial infarction." (PMID 37834303, 2023). "Importantly, IL-6 and IL-17A produced post-myocardial infarction may cause neuroinflammation, and mancostemonin attenuates this process." (PMID 40276600, 2025). "Evidence indicates that IL-17A may have a safeguarding role in certain scenarios, like in individuals experiencing a heart attack, where reduced levels of IL-17A in the bloodstream have been associated with mortality and repeated severe cardiovascular incidents." (PMID 39844544, 2025). "In humans, an acute myocardial infarction registry demonstrated that serum IL-17A below a median of 6.26 pg/mL was associated with higher risk for all-cause mortality and recurrent myocardial infarction, but many patients had IL-17A levels below the assay’s detection limit of 2.5 pg/mL." (PMID 30109481, 2018). "In a mouse model of myocardial infarction induced by coronary artery ligation, a notable increase in IL-17A and IL-17RA expression was observed in the heart." (PMID 39502194, 2024). "In vivo, the administration of recombinant mouse IL-17A promoted myocardial fibrosis and ventricular remodeling 28 days after myocardial infarction in mice, compared to the myocardial infarction group." (PMID 39502194, 2024). "Emerging studies have identified that immune cells infiltrate myocardial tissue during myocardial infarction and release a large number of pro-inflammatory cells, including IL-1β, IL-6, IL-17A and TNF-α." (PMID 36483733, 2022). "In the present study, we found that levels of IL-17A in plasma were also significantly increased during the progression of HF, initiating within 1 week with a peak level measured at 4 weeks after myocardial infarction." (PMID 36312009, 2022). "Other results show that IL-17A favors aneurysm formation, myocardial infarction, stroke and hypertension." (PMID 35479069, 2022). "After acute myocardial infarction, IL-17A aggravates inflammatory response and ischemic injury by inducing macrophages infiltration, and NLRP3 inflammasome and p38 MAPK are significantly activated." (PMID 33171330, 2021). "In a more acute situation, a peak of bioactive IL-17A occurred at the time of admission in patients with myocardial infarction." (PMID 32983142, 2020). "In line with this, repletion of interleukin 17 (IL-17A) in IL-17A knockout mice aggravated acute and chronic cardiac remodeling, increased infarct size, and induced cardiomyocytes apoptosis in a myocardial infarction model." (PMID 30203627, 2018).
myocardial infarction (continued). "Our study has four main findings: 1) IL-17A prior to reperfusion and in the first hours following reperfusion was significantly increased at the acute phase of myocardial infarction when compared to healthy controls." (PMID 29166391, 2017). "Interleukin 17A (IL17A) concentrations are higher in male patients with acute myocardial infarction than in women." (PMID 28352449, 2014). "In this study, we detected the plasma IL-17A levels and platelet aggregation in patients with stable angina (SA), unstable angina (UA), acute myocardial infarction (AMI) and chest pain syndrome (CPS)." (PMID 22808218, 2012). "Intriguingly, Interleukin-17A (IL-17A) is an inflammatory cytokine that exacerbates the cardiovascular system and plays a crucial role in the development of cardiovascular diseases and myocardial infarction and responsible for pathogenesis of multiple autoimmune and inflammatory conditions." (PMID 40064794, 2025). "Additionally, another study revealed that IL-17A knockout mice exhibited a 30% increase in survival rate at day 28 compared to mice with a myocardial infarction model." (PMID 39502194, 2024). "Similarly, patients with myocardial infarction show a peak of circulating IL-17A at admission." (PMID 35479069, 2022). "The present study sought to determine whether IL-17A levels are elevated in a rat model of HF induced by myocardial infarction and, if so, whether increased expression of IL-17A in the brain itself contributes to neuroinflammation and cardiac dysfunction in this disease setting." (PMID 36312009, 2022). "Thus, low serum levels of IL-17A have been associated with a higher risk of major cardiovascular events in Caucasian patients with acute MI16, and in a murine model of myocardial infarction, IL-17A promoted stabilization of atherosclerotic plaques through an interleukin-17-dependent pathway." (PMID 29062018, 2017). "Consistently, plasma IL-17A levels were significantly elevated in patients who experienced CA after myocardial infarction compared with non-CA controls." (PMID 42136658, 2026). "Importantly, our data extend previous findings by displaying that the levels of IL-17A in the brain CSF and PVN were also significantly elevated after myocardial infarction, which correlate well with its levels measured in the plasma." (PMID 36312009, 2022). "Using this bioassay, increased levels of bioactive IL-17A were found in RA patients with joint destruction compared to those without and patients with myocardial infarction showed a peak of bioactive IL-17A at admission." (PMID 32983142, 2020). "Furthermore, in a mouse model of myocardial infarction, TNF-α mRNA, IL-1α, IL-2, IL-4, IL-5, IL-6, IL-10, IL-17A, TNF-α, IFN-γ, and GM-CSF expression were all lower in the infarct area of TLR4-deficient mice compared with wild-type mice." (PMID 30399158, 2018).
Sjögren’s syndrome (65 papers, 2011 to 2026). "Recent studies have also linked IL-17A to ocular pathogenesis of Sjögren's Syndrome." (PMID 21298010, 2011).